HIF1A (hypoxia inducible factor 1 subunit alpha)
Diseases named in the same sentence as HIF1A in open-access papers (continued):
Sharing a sentence is not in itself a finding about the gene and the disease.
cancer (continued). "It is reported that HIF-1α has an anti-apoptosis effect on cancer cells." (PMID 31849679, 2019). "A connection between HIF-induced TG synthesis and cell proliferation is supported by metabolic profiling analysis of cancer cells kept under hypoxia, which has shown that the concentration of TAGs and derivative phospholipids PC and PE is substantially increased in a HIF-1α-dependent manner." (PMID 30832409, 2019). "Exposure to elevated levels of ROS can lead to cancer cell resistance by the activation of redox-sensitive transcription factors such as NF-κB, nuclear factor (erythroid-derived 2)-like factor 2 (Nrf2), c-Jun, and HIF-1α." (PMID 31711497, 2019). "LSD1, through HIF-1α stabilization, induces genes involved in glycolysis in cancer cells." (PMID 30866496, 2019). "This strongly suggests that ROS may regulate the expression of a broad range of miRNA genes in cancer by regulating the redox-sensitive HIF-1α transcription factor." (PMID 31717786, 2019). "It would be interesting to investigate whether the modulation of GHET1 for the interaction of VHL and HIF1α also occurs in other types of cancers." (PMID 30988076, 2019). "Recently, it was demonstrated that ELK3 regulates hypoxia-induced factor 1α (HIF-1α); HIF-1α is a transcription factor that has an essential role in the regulation of genes associated with cancer metastasis, invasion, angiogenesis, cellular proliferation, apoptosis, and glucose metabolism." (PMID 31018569, 2019). "HIF-1α gene SNPs are more frequent in several cancers than in healthy groups." (PMID 30678691, 2019). "Tissue hypoxia occurs due to an inadequate amount of oxygen delivery or due to cancer cell metabolism re-programming, rendering cancer cells to adapt to less oxygen by up-regulating several key proteins, including hypoxia-inducible factor-1α (HIF-1α), HIF-2α." (PMID 31245292, 2019). "On the basis of these results, we hypothesized that miR-181c elevation might be a molecular link between NRF2-silencing and HIF-1α dysregulation in cancer cells." (PMID 31078780, 2019). "We propose that the protumorigenic role of HIF1α in VHL cancers may be blunted through drugs inhibiting mitochondrial respiratory complexes, such as metformin." (PMID 30728892, 2019). "Since HIF-1α is an important cellular transcription factor for numerous metabolic genes dysregulated in cancers, future studies should explore whether HIF-1α is responsible for the metabolic changes induced during VACV infection." (PMID 31319842, 2019). "In addition to the pVHL, HIF-1α and UCP proteins, a variety of modulators of HIF-1α have been implicated in carcinogenesis and cancer metastasis, as recently reviewed by Aldo and Elisabetta66." (PMID 31221957, 2019). "Hypoxia inducible factor 1 (HIF1α) as a major transcription factor in cancer." (PMID 32010625, 2019). "The C1772T SNP has been reported to increase HIF-1α protein expression in some cancers." (PMID 30678691, 2019). "Cancer cells trigger HIF‐1A signaling upon hypoxia conditions." (PMID 30538116, 2019). "Due to the role of HIF-1α in aerobic glycolysis and mitochondrial function, it has been proposed that HIF-1α inhibition could be a therapeutic strategy to treat cancer." (PMID 31261749, 2019). "This connection is therapeutically valuable and should be considered in developing novel therapies with an effect upon activated HIF-1α; moreover, hypoxia regulates not only cancer progression through angiogenesis and metastasis but also the resistance to therapy." (PMID 31652660, 2019). "In addition, HIF-1α itself was found in exosomes with transcriptional activity which has been widely accepted as a good biomarker to predict cancer progression as well as treatment outcomes." (PMID 30925935, 2019). "By contrast, a study from Russel and Ohh reported that in different cancer cell lines direct NEDDylation of pVHL may negatively regulate HIF-1α ubiquitination leading to its stabilization." (PMID 31817100, 2019).
cancer (continued). "Our studies support the hypothesis that through the DNA damage and repair machinery RAD51 might contribute to cancer cell glycolysis by regulating the HIF1α transcriptional process." (PMID 31889908, 2019). "Several studies have found that HIF-1α enhances glycolysis by upregulating glycolytic enzymes, and upregulates PD-L1, which suggests a potential link between PD-L1 and glycolysis in cancer." (PMID 31718692, 2019). "HIF-1α was increased in cancer cells in the AMD3100-treated mice compared to the untreated mice." (PMID 31336612, 2019). "Hypoxia and subsequent stabilization of HIF-1α induce downstream metabolic changes in cancer cells." (PMID 31536495, 2019). "Furthermore, cancer stem cells can survive under hypoxic conditions by promoting the production of hypoxia-inducible factor (HIF)-1α, VEGF, and proangiogenic factors." (PMID 31906017, 2019). "HK2 has been described as a target of the HIF1a protein in several cancers, including RCC." (PMID 31878355, 2019). "It was previously reported that cancer cells expressing both HIF-1α and HIF-2α proteins might mutually compensate by upregulating HIF-1α under HIF-2α knockdown conditions, favoring a malignant phenotype." (PMID 30642030, 2019). "Thus, the blockage of adaptive responses mediated by VEGF/HIF1A in cancer cells represents a convergent anti-survival effect evoked by AVAs." (PMID 31540249, 2019). "However, the significant role of HIF-1α on the metastatic potential and cancer progression is studied only in gastric cancer but is yet to be investigated in other metastatic cancers." (PMID 30754624, 2019). "It is well known that HIF-1α increases the glycolytic activity of cancer cells, resulting in the overexpression of glycolytic key enzymes like hexokinases (HK) or lactate dehydrogenase (LDH-A), and glucose and lactate transporters such as the GLUT-1, GLUT-3, and MCT-4." (PMID 31744229, 2019). "However, from our results, among MO-460 targets, hnRNPA2B1 seems to be valuable as an anti-cancer target on HIF-1α inhibition." (PMID 30755586, 2019). "Rapamycin also negatively regulates VEGF, platelet-derived growth factor (PDGF), basic fibroblast growth factor (bFGF) and so on, which are transcriptional targets of hypoxia-inducible factor 1α (HIF-1α) and contribute to vascular development and cancer progression." (PMID 30754640, 2019). "Systemic administration of glutaminase inhibitors suppressed the growth of RCC cells as xenografts in mice, while recent studies have shown that modulation of HIF-1α phosphorylation can regulate LD accumulation and cancer cell growth, specifically under hypoxia." (PMID 30832409, 2019). "Moreover, these vessels were located in areas surrounded by hypoxia and HIF-1α-positive cancer cells, suggesting that they were most likely generated via HIF1-mediated signals." (PMID 30796225, 2019). "Therefore, HIF-1, particularly HIF-1α, has been extensively studied as a potential drug target for cancer chemotherapy." (PMID 30857246, 2019). "An analysis of the underlying molecular mechanisms revealed that 14-3-3η stabilizes hypoxia-inducible factor 1α (HIF-1α) through the inhibition of ubiquitin-dependent proteasome protein degradation, which leads to the maintenance of cancer stem cell (CSC) properties." (PMID 31341646, 2019). "Our observations that tamoxifen can negatively regulate HIF‐1A in cancer cells through a hypoxia‐independent mechanism open up the possibility to reprogram the mechanosensory machinery in these cells to modulate their proliferation under hypoxic conditions by targeting HIF‐1A." (PMID 30538116, 2019). "Thus, we identified a novel HIF-1α inhibitor from the metabolites of Streptomyces flavoretus, which shows promising anti-cancer potential." (PMID 31083403, 2019). "Cancer cells in humans have overexpression of HIF-1α, but this is dependent on the type of cancer." (PMID 31485300, 2019). "There are also clinical studies that aim to inhibit HIF1α in cancer therapy." (PMID 31554283, 2019).
cancer (continued). "As a transcription factor, HIF-1α directly regulates gene expressions of many target proteins involved in cancer angiogenesis, especially under hypoxia, and vascular endothelial growth factor (VEGF) is the target gene which is closely associated with angiogenesis." (PMID 31320912, 2019). "Hypoxia-inducible factor 1α (HIF-1α) is the master regulator of cancer cell metastasis." (PMID 31817810, 2019). "For example, the Hypoxia Inducible Factor Alpha subunit (HIF1A) is a transcription factor that is known for its role in mediating the hypoxic response and it was shown to correlate with poorer prognosis in various types of cancer." (PMID 31067678, 2019). "To understand contributing factors that may be supporting NANOG activation and cancer stemness, we also checked β‐catenin and HIF‐1α as a known activator of P4HA2." (PMID 31268606, 2019). "miR-21 in various cancers can activate HIF-1α signals to promote cell proliferation." (PMID 30824757, 2019). "The development of new drugs targeting both the core circadian machinery and HIF-1α is an emerging area of research that may prove a useful anti-cancer strategy." (PMID 33089179, 2019). "Taken together, these data likely support a NRF2- HIF-1α-miR-210-3p axis as a further mechanism by which miR-210-3p might promote taxane resistance in cancer cells." (PMID 31624308, 2019). "YAP luciferase activity in presence of HIF-1α was promoted in rhHMGB1 treated CD133− cancer cells." (PMID 31558702, 2019). "Indeed, enhanced HIF-1α expression has been detected in various cancers, including lung, breast, colon, and liver cancers, and is significantly correlated with low patient survival rates." (PMID 31817259, 2019). "Moreover, YAP nuclear translocation was significantly inhibited in HIF-1α knockdown CD133− cancer cells in the presence of rhHMGB1 treatment." (PMID 31558702, 2019). "Another pathway involved in EMT and regulated by ROS is the transcription factor hypoxia inducible factor 1-alpha (HIF-1α), which is induced under hypoxic conditions and can stimulate cancer cell EMT by activating EMT-inducing transcription factors such as Twist, Snail and ZEB1/2." (PMID 31921862, 2019). "Hypoxic conditions in cancer may affect the autophagy pathway to enable cancer cells to adapt and survive under low oxygen conditions via the stress response signaling pathway, such as hypoxia-inducible factor-1 alpha (HIF-1α)." (PMID 30400561, 2018). "It would be interesting to assess whether in human cancer cells, hypoxia-activated HIF-1α may lead to ligand-independent activation of Notch signaling by mimicking the effect of Sima on Notch endocytic trafficking." (PMID 29996493, 2018). "To address this challenge, we report a robust in vitro cancer dormancy model under a hypoxia-mimicking microenvironment using cobalt chloride (CoCl2), a hypoxia-mimetic agent, which stabilizes hypoxia inducible factor 1-alpha (HIF1α), a major regulator of hypoxia signaling." (PMID 30127847, 2018). "Hypoxia inducible factor 1α (HIF-1α) is a major cancer driver and a potential therapeutic target." (PMID 29910728, 2018). "Additionally, increasing evidence has suggested that HIF-1α improves the glycolytic flux of cancer cells, which plays a critical role in promoting chemoresistance of NSCLC cells." (PMID 29898734, 2018). "In cancer cells, both HIF1A and GLUT1 were found to be upregulated." (PMID 30217067, 2018). "In addition, clinical and/or preclinical inhibitors of signaling pathways involved in regulating HIF-1α expression used in this study also present as new strategies for treatment of human cancer." (PMID 29587825, 2018).
cancer (continued). "Indeed, HIF-1α is involved in the regulation of a two-compartment metabolic symbiosis between anabolic cancer cells and catabolic stromal fibroblasts." (PMID 29996493, 2018). "Thus, many WNT/β-catenin target genes such as c-Myc, cyclin D1, and HIF-1α are involved in the development of cancers." (PMID 29706964, 2018). "Similarly, in different types of cancer cells hypoxia-activated HIF-1α has been shown to promote EMT by potentiating the Notch signaling pathway." (PMID 29996493, 2018). "IFN was used to induce inflammation response and HIF-1α expression in various cancer cell lines." (PMID 29587825, 2018). "Moreover, to enhance the constitutive expression of HIF-1α in these cancer cells, the co-culture was incubated with cobalt chloride, which has the ability to stabilize HIF-1α and activate the transcription factor, HIF-1." (PMID 30138430, 2018). "The grouping of pro-collagen molecules to form collagen fibrils requires the presence of prolyl-4-hydroxylases and procollagen lysyl hydroxylases, and HIF-1α can upregulate the expression of specific subunits of these enzymes in cancer cells, including prolyl 4-hydroxylase subunit alpha 1/2." (PMID 30487436, 2018). "In addition, Na+/K+-ATPase inhibitors are able to downregulate the expression of HIF-1α in cancer cells." (PMID 29946188, 2018). "Although HIF1α drives the M1 phenotypes in hypoxic conditions, lactate produced by cancer cells, as a by-product of aerobic glycolysis, has an unexpected critical function in HIF1α-dependent expression of ARG1 and resultant M2-like activation of TAMs in normoxic conditions." (PMID 29651445, 2018). "APE1/Ref-1 is a multifunctional protein that was initially discovered as an enzyme in the base excision repair (BER) pathway, but has also emerged as a redox-signaling regulator of a number of transcription factors known to be involved in cancer, namely NFĸB, AP-1, HIF1a, and STAT3." (PMID 29541389, 2018). "In cancer cells, when the level of oxygen is low, pyruvate is prevalently converted to lactate instead of acetyl CoA; hypoxia induces the expression of HIF-1α which, in turn, regulates the expression of several genes, some of which are involved in the glycolytic pathway." (PMID 29584711, 2018). "In cancer cells, macrophages, dendritic cells and MDSCs, HIF1-α directly induces PD-L1 expression." (PMID 29362402, 2018). "Besides the stability regulation, HIF-1α protein synthesis can be activated in cancer cells through the phosphatidylinositol-3-kinase (PI3K)–Akt signaling axis primarily by the action of mammalian target of rapamycin complex 1 (mTORC1)." (PMID 29435158, 2018). "Nonetheless, it remains uncertain whether HIF-1α and its downstream targets are also involved in cancer-related EndoMT." (PMID 29435158, 2018). "It seems that PRODH/POX-dependent inhibition of HIF-1α could play important role in inhibition of cancer cell growth and invasion." (PMID 29568391, 2018). "al. suggested that cancer associated fibroblasts (CAFs) promote PKM2 nuclear translocation through both oxidation and Src-mediated phosphorylation, and also demonstrated that nuclear PKM2 was associated with HIF-1α and caused EMT." (PMID 30333907, 2018). "In many cancers, the synthesis of HIF-1α is strictly related to mTOR activity." (PMID 30510924, 2018). "The proposed mechanism included HIF-1α-promoted autophagy, mitophagy, and the production of lactate and recyclable nutrients, which could fuel cancer cells and provide them with building blocks." (PMID 29362402, 2018). "Furthermore, we demonstrated that PTGIS is a HIF-1α targeted gene, a major regulator in hypoxic cancer progression by activating transcription of various oncogenes." (PMID 30315244, 2018). "We showed for the first time that IFN induced functional HIF-1α expression in a time- and dose- dependent manner in various cancer cell lines under both hypoxic and normoxic conditions, and then leading to an activated HIF-1α pathway in an IFN-mediated pro-inflammatory TME." (PMID 29587825, 2018).
cancer (continued). "In addition, they also seem to induce autophagy in cancer cells by inhibiting hypoxia-inducible factor 1alpha (HIF1α), mammalian target of rapamycin (mTOR), and ERK1/2." (PMID 30373171, 2018). "Hypoxia-inducible factor-1 α (HIF-1α) links inflammation to cancer." (PMID 30583572, 2018). "HIF-1α is also often overexpressed in several other cancers." (PMID 29594129, 2018). "Likewise, we highlight studies giving insights into the interplay between HIF-1α and Notch signaling in cancer EMT." (PMID 29996493, 2018). "Similarly, Parp-1 directly interacts with the HIF-1α protein and contributes to its activation in several human cancer cell lines as well as murine embryonic fibroblasts." (PMID 29755367, 2018). "SIRT3 destabilizes HIF1α induced metabolic reprogramming in cancer cells." (PMID 30250024, 2018). "Cells surpassing the mutation threshold showed also a profound metabolic remodeling and chronic destabilization of the Hypoxia Inducible Factor 1α (HIF-1α), preventing the hypoxic and metabolic adaptation necessary for cancer cells to proceed toward malignancy." (PMID 29518970, 2018). "Thus, our 3D microvasculature model served to investigate the extravasation potential of hypoxic human breast epithelial and cancer cell lines while confirming the implication of HIF-1α in this process." (PMID 30560881, 2018). "In addition, miR-26a expression levels negatively correlate with Bax, Bad levels, and GBM progression; but highly correlate with HIF-1α levels in clinical cancer tissues." (PMID 30425242, 2018). "However, some studies described a linear correlation between the HIF-1α mRNA and HIF-1α protein expression for several types of cancers." (PMID 30513863, 2018). "For validation, over-activation of the key proteins in PI3K/Akt/HIF-1α signaling pathways were detected in dysplasic lesions and cancers from hamsters and Sal-B treatment significantly inhibited the signaling pathway that is constitutively activated in human OSCC28." (PMID 29789538, 2018). "HIF-1α is also involved in the maintenance of cancer stem cells." (PMID 30029472, 2018). "The classic example of redox sensing in cancer is the stabilization of the transcription factor hypoxia-inducible factor 1α (HIF1α) that allows solid tumors to adapt to low-oxygen stress by promoting aerobic glycolysis (Warburg’s effect), angiogenesis, and tumor invasion." (PMID 29337889, 2018). "Studies have established beneficial role in targeting Hif1α in cancer therapy." (PMID 29636643, 2018). "We found that according to the KEGG enrichment of the common DEGs deregulated upon SOX2OT inhibition; the pathways related to cancer (Kegg: 05200) is one of the most significant enriched pathway (p-value = 0.009285) with 6 genes (HIF1A, HRAS, CHUK, PIK3CA, CDK2, VHL)." (PMID 30202240, 2018). "A novel small molecule named saltern amide A (SA) can inhibit HIF-1α in various human cancer cells." (PMID 29560266, 2018). "HIF-1α dependent activation of NF-κB has also been demonstrated in cancer cell lines." (PMID 29568285, 2018). "Several inhibitors targeting HIF-1α pathway have also been developed for cancer therapeutics." (PMID 29435158, 2018). "Inhibition of VEGF and HIF-1α reduces the angiogenesis of cancer." (PMID 30445746, 2018). "Moreover, TG2 is included in the activation of other pathways, such as NF-κB, HIF1α, etc., all of which are responsible for cancer progression." (PMID 30200219, 2018). "HIF1A/PDL1 axis plays a significant role in PDL1 up-regulation in different types of cancer." (PMID 30393513, 2018). "NOS2 can regulate cancer proliferation via increasing the stability of HIF-1a." (PMID 30381359, 2018). "HIF-1α stabilises multiple adaptive responses to hypoxia, such as angiogenesis, proliferation and metabolism by coordinating the altered metabolic circuitry of the cancer cell, triggering the up-regulation of some genes that play a role in aerobic glycolysis." (PMID 30544833, 2018).